TRIM17 (tripartite motif containing 17)
Description:
E3 ubiquitin ligase that plays important roles in the regulation of neuronal apoptosis, selective autophagy or cell proliferation. Stimulates the degradation of kinetochore ZW10 interacting protein ZWINT in a proteasome-dependent manner, leading to negative regulation of cell proliferation. Inhibits autophagic degradation of diverse known targets while contributing to autophagy of midbodies. Autophagy-inhibitory activity involves MCL1, which TRIM17 assembles into complexes with the key autophagy regulator BECN1. Controls neuronal apoptosis by mediating ubiquitination and degradation of MCL1 to initiate neuronal death. In addition, regulates NFAT transcription factors NFATC3 and NFATC4 activities by preventing their nuclear localization, thus inhibiting their transcriptional activities. Decreases TRIM41-mediated degradation of ZSCAN2 thereby stimulating alpha-synuclein/SNCA transcription in neuronal cells (By similarity). Prevents the E3 ubiquitin-ligase activity of TRIM28 and its interaction with anti-apoptotic BCL2A1, blocking TRIM28 from ubiquitinating BCL2A1.
Synonyms: RBCC; RNF16; TERF
Tractability: PROTAC: UniProt records ubiquitination sites on it; ubiquitination databases record sites on it.
Gene: Protein-coding gene on chromosome 1 (228,406,860 to 228,416,902, reverse strand). Ensembl gene ENSG00000162931.
Subcellular location: Cytoplasm; Lysosome
Subcellular location (Human Protein Atlas): Vesicles
Pathways (Reactome):
Immune System: Interferon gamma signaling
Gene Ontology:
Molecular function: protein binding; protein-macromolecule adaptor activity; ubiquitin-protein transferase activity; ubiquitin protein ligase activity; zinc ion binding
Biological process: autophagy; protein autoubiquitination; regulation of protein localization; innate immune response; regulation of gene expression; protein ubiquitination
Cellular component: cytoplasm; lysosome
Genetic constraint (gnomAD): Loss-of-function variants: 27 observed, 36.48 expected, observed/expected ratio (o/e) 0.74, 90% interval 0.54 to 1.02. The upper end of that interval is the gene's LOEUF score, 1.02, which puts it in group 4 of 6, group 1 being the genes least tolerant of losing a copy. Missense variants: 582 observed, 632.03 expected, observed/expected ratio (o/e) 0.92, 90% interval 0.86 to 0.99. Synonymous variants: 246 observed, 258.49 expected, observed/expected ratio (o/e) 0.95, 90% interval 0.86 to 1.06.
Homologues: Orthologues: chimpanzee TRIM17 (99% identical), macaque TRIM17 (96% identical), rabbit TRIM17 (80% identical), pig TRIM17 (77% identical), mouse Trim17 (77% identical), guinea pig TRIM17 (76% identical), rat Trim17 (75% identical). Paralogues in human: TRIM11 (46% identical), TRIM27 (37% identical), TRIM39 (36% identical), TRIM41 (35% identical), TRIM58 (35% identical), TRIM4 (34% identical), TRIM21 (32% identical), TRIM7 (31% identical), TRIM68 (28% identical), TRIML1 (28% identical), TRIM38 (28% identical), TRIM26 (27% identical), and 68 more.
Diseases named in the same sentence as TRIM17 in open-access papers:
TRIM17 is named in the same sentence as 29 diseases in open-access papers, as found by Europe PMC text mining. Sharing a sentence is not in itself a finding about the gene and the disease. The quoted sentences say what the papers report.
glioma (5 papers, 2022 to 2023). A benign or malignant brain and spinal cord tumor that arises from glial cells (astrocytes, oligodendrocytes, ependymal cells). "Our results demonstrated that DNA methylation of TRIM family members, specifically, TRIM17/21/22/24/28, perform significantly lower methylation levels collectively, in association with gliomas of WHO IV versus WHO II and III." (PMID 37367937, 2023). "Our study disclosed that the expression of TRIM17 was lower in glioma and its subtype samples than in normal ones." (PMID 37367937, 2023). "At the same time, through GEPIA2, we discovered that the mRNA expression of TRIM5/21/22/24/28/34/47 was significantly up-regulated in different LGG and GBM histological subtypes, while the expression of TRIM17 was down-expressed in diverse gliomas subtypes." (PMID 37367937, 2023). "In vitro, TRIM17 overexpression ablates glioma cell line colony formation, aligning with data showing that TRIM17 overexpression in cerebellar neurons induces apoptosis, dependent on its RING domain." (PMID 38115822, 2023). "While TRIM17 performs in an adverse state, showing a lower expression level in glioma, LGG, and GBM tissues compared to the normal." (PMID 37367937, 2023). "Functional assays on glioma cell lines supported a tumor suppressive role for TRIM17 involving suppression of cell proliferation." (PMID 36139694, 2022). "Understanding and harnessing the pro-apoptotic function of TRIM17 may be a powerful tool to fight glioma." (PMID 38115822, 2023). "Besides, extracting the data from CGGA, we performed methylation analyses, the outcomes showed that the methylation levels of TRIM17/21/22/24/28 in WHO IV gliomas were significantly lower than that in WHO II and WHO IV (P < 0.001)." (PMID 37367937, 2023). "Importantly, TRIM17 was downregulated in gliomas compared to normal brain tissue, and its expression was inversely correlated with tumor grade." (PMID 36139694, 2022). "However, there are only a few explorations on the characteristics of TRIM17 in gliomas." (PMID 37367937, 2023). "In addition, survival analysis revealed that the high expression profiles of TRIM5/21/22/24/28/34/47 were associated with poor overall survival (OS), disease-specific survival (DSS) and progress-free interval (PFI) in glioma patients, whereas TRIM17 displayed adverse outcomes." (PMID 37367937, 2023). "More importantly, higher mRNA expression of TRIM17 was also significantly related to a longer OS, DSS, PFI of glioma patients." (PMID 37367937, 2023). "TRIM17-mediated neuronal apoptosis in that context is part of an orchestrated programme required for proper cerebellar developmental morphogenesis and is responsive to neurotrophic factor signaling through the PI3K/Akt/GSK signaling axis, which is, interestingly, also upregulated in glioma." (PMID 38115822, 2023). "Although having not been reported in glioma-related research, TRIM34, PCGF2, TLE3, and TRIM17 have been revealed to contribute to the carcinogenesis of other cancers." (PMID 35832194, 2022).
melanoma (5 papers, 2021 to 2025). A malignant, usually aggressive tumor composed of atypical, neoplastic melanocytes. "TRIM17 augments BRAF-targeted therapy sensitivity of melanoma cells by preventing BCL2A1 from being ubiquitinated and degraded by TRIM28." (PMID 35832194, 2022). "More interestingly, KO of TRIM17 restored sensitivity to PLX4720 in resistant melanoma cells, by relieving the inhibition of TRIM28-mediated ubiquitination of BCL2A1 and thereby by reducing BCL2A1 level." (PMID 34069831, 2021). "Indeed, we found that TRIM17 expression is induced in melanoma cells following treatment with the BRAF inhibitor PLX4720." (PMID 34069831, 2021). "TRIM17 and TRIM28 are identified as antagonistic regulators that maintain the balance of BCL2A2 protein levels, thereby modulating melanoma progression." (PMID 41315179, 2025). "For example, TRIM17 binds to BCL2A1 and prevents TRIM28-mediated ubiquitination and degradation of BCL2A1 in melanoma cells." (PMID 33966039, 2021). "These regulatory phenomena have important consequences in melanoma treatment, where either TRIM28 overexpression or TRIM17 knockout lowers BCL2A1 protein levels and restores melanoma cell susceptibility to B-Raf protooncogene and serine/threonine kinase (BRAF)-directed therapy." (PMID 38225560, 2024).
breast carcinoma (4 papers, 2017 to 2023). "For example, TRIM44 has been found to bind TRIM17 in a yeast two-hybrid assay (Y2H) using the tripartite motif of TRIM17 as a bait to screen a prostate/breast cancer cDNA library." (PMID 34069831, 2021).
gastric cancer (4 papers, 2025). A primary or metastatic malignant neoplasm involving the stomach. "TRIM17 was inversely associated with BAX expression levels in gastric cancer cells." (PMID 40936722, 2025). "On the other hand, TRIM17 has been shown to promote the proliferation of gastric cancer cells via ubiquitination-mediated proteasomal degradation of apoptotic protein BAX." (PMID 39851497, 2025). "TRIM17 is significantly upregulated in gastric cancer and is closely related to the prognosis of patients." (PMID 41145484, 2025). "This is different from the pattern mentioned in the introduction that TRIM17 promotes cell survival by degrading BAX in gastric cancer." (PMID 41145484, 2025). "This work also demonstrated that TRIM17 is transcriptionally upregulated in gastric cancer patients, while BAX expression is inversely related to TRIM17 in those cohorts." (PMID 39851497, 2025). "This regulatory pattern is different from the mechanism by which TRIM17 inhibits apoptosis by degrading BAX in gastric cancer, suggesting that TRIM17 may exert a pro-cancer effect by targeting specific substrates in different tumors." (PMID 41145484, 2025). "In addition, TRIM17 acts as a negative regulator of the apoptotic reaction and is triggered by cancer treatments; Knockdown of TRIM17 was observed to improve the efficacy of chemotherapy, demonstrating therapeutic potential in gastric cancer." (PMID 40936722, 2025). "Another study shows that TRIM17, through interaction with BAX, which results in its proteasomal degradation, led to the inhibition of apoptosis and excessive cell proliferation in the gastric cancer cell lines AGS and HGC-27." (PMID 41614769, 2025).
osteosarcoma (3 papers, 2021 to 2025). A usually aggressive malignant bone-forming mesenchymal neoplasm, predominantly affecting adolescents and young adults. "In summary, this study elucidates the role of TRIM17 in osteosarcoma progression and its underlying molecular mechanisms." (PMID 41145484, 2025). "Elevated TRIM17 expression is associated with poor prognosis in osteosarcoma patients." (PMID 41145484, 2025). "Survival analysis revealed that TRIM17 was associated with poor prognosis in osteosarcoma patients." (PMID 41145484, 2025). "In recent years, TRIM17 has been implicated in the development of various tumors, particularly in cancer cell clonability and survival potential and drug resistance; however, its regulatory mechanism in osteosarcoma progression remains poorly understood." (PMID 41145484, 2025). "The effects of TRIM17 on osteosarcoma cell clonability and survival potential, migration, and invasion were assessed through phenotypic assays." (PMID 41145484, 2025). "TRIM17 represents a novel therapeutic target for osteosarcoma, and its combination with other targeted therapies or immunotherapies is expected to enhance treatment efficacy and improve patient outcomes." (PMID 41145484, 2025). "In conclusion, we have elucidated the mechanism by which TRIM17 positively regulates osteosarcoma progression." (PMID 41145484, 2025). "The assayal results showed that the SC tumors of nude mice in the shTRIM17 group were much smaller in volume and weight than those in the control group, suggesting that inhibiting TRIM17 expression in vivo can suppress the growth of osteosarcoma." (PMID 41145484, 2025). "In conclusion, TRIM17 likely modulates osteosarcoma malignancy through regulation of the AKT/mTOR signaling pathway." (PMID 41145484, 2025). "It is worth emphasizing that the conclusion in this study that TRIM17 promotes the progression of osteosarcoma by activating the mTOR pathway is highly consistent with previous studies." (PMID 41145484, 2025). "In this study, we observed that TRIM17 expression was significantly elevated in osteosarcoma tissues compared to adjacent normal tissues, as well as in osteosarcoma cells, and high TRIM17 expression was associated with poor prognosis in osteosarcoma patients." (PMID 41145484, 2025). "We injected 143B osteosarcoma cells with stable TRIM17 knockdown or control cells into the flanks of nude mice, monitored the tumor development of the mice, and measured tumor size every 7 days." (PMID 41145484, 2025). "Venn diagram analysis of the survival and differential expression results demonstrated that TRIM26 and TRIM17 were differentially expressed in osteosarcoma and correlated with patient prognosis." (PMID 41145484, 2025). "The results showed that the downregulation of TRIM17 significantly inhibited osteosarcoma cell clonability and survival potential, migration, and invasion, whereas its overexpression promoted these processes." (PMID 41145484, 2025). "In conclusion, knockdown of TRIM17 can significantly inhibit the clonability and survival potential, migration, and invasion of osteosarcoma in vitro." (PMID 41145484, 2025). "Silencing the expression of TRIM17 in osteosarcoma cells reduced their malignant characteristics, whereas overexpression of TRIM17 had the opposite effect." (PMID 41145484, 2025). "Future studies should focus on a deeper exploration of TRIM17’s regulatory mechanisms in osteosarcoma and its interactions with other signaling pathways to develop more effective therapeutic strategies." (PMID 41145484, 2025). "In vitro assays demonstrated that silencing TRIM17 can inhibit the clonability and survival potential, migration, and invasion of osteosarcoma, whereas TRIM17 overexpression promoted these malignant behaviors." (PMID 41145484, 2025).
osteosarcoma (continued). "Analysis of tissues and osteosarcoma cell lines from clinical patients revealed that TRIM17 expression was significantly elevated in osteosarcoma, and high TRIM17 expression correlated with poor prognosis in osteosarcoma patients." (PMID 41145484, 2025). "The results indicated that the expression of TRIM17 in osteosarcoma tissues was increased compared with adjacent normal tissues." (PMID 41145484, 2025). "As the mechanism of TRIM26 in osteosarcoma has been previously investigated, this study focuses on exploring the role of TRIM17 in osteosarcoma." (PMID 41145484, 2025). "TRIM17 was shown to play a vital role in regulating tumorigenesis and chemoresistance in osteosarcoma via ubiquitination of breast cancer metastasis suppressor 1 (BRMS1)." (PMID 37591850, 2023). "Finally, we injected stably transfected osteosarcoma cells into mice via the tail vein to construct a lung metastasis model of osteosarcoma, through which we investigated the effect of silencing TRIM17 on distant metastasis of osteosarcoma in vivo." (PMID 41145484, 2025). "We found that TRIM17 was significantly upregulated in osteosarcoma tissues and cells." (PMID 41145484, 2025). "ROC curve analysis showed that TRIM17 expression level could accurately predict the prognosis of osteosarcoma patients (AUC: 0.703)." (PMID 41145484, 2025). "In addition, the TRIM17 protein and mRNA levels in osteosarcoma cell lines (HOS, MG63, Saos-2, U2OS, 143B) were significantly higher than those in normal osteoblasts (hFOB1.19)." (PMID 41145484, 2025). "TRIM17 may represent a potential therapeutic target for the clinical management of osteosarcoma patients." (PMID 41145484, 2025). "We further investigated the mechanism of action of TRIM17 in osteosarcoma." (PMID 41145484, 2025). "However, the role of TRIM17 in the occurrence and development of osteosarcoma, as well as its specific mechanisms of action, remain to be further studied." (PMID 41145484, 2025). "In summary, our findings suggest that TRIM17 may serve as a potential prognostic marker and therapeutic target for osteosarcoma." (PMID 41145484, 2025). "Based on these findings, we hypothesized that TRIM17 modulates osteosarcoma progression by regulating the AKT-mTOR signaling pathway." (PMID 41145484, 2025). "Therefore, TRIM17 functions as a potential oncogene in osteosarcoma, promoting tumor malignancy, and represents a potential therapeutic target for osteosarcoma patient." (PMID 41145484, 2025). "To further verify the role of TRIM17 in osteosarcoma, we conducted immunohistochemical analysis on 12 groups of osteosarcoma tissues and adjacent normal tissues collected in the hospital (the results of two representative groups of immunohistochemistry are shown in the figure)." (PMID 41145484, 2025). "Therefore, our assayal results suggest that TRIM17 regulates the expression of PDK1 through FTO-mediated m6A demethylation in osteosarcoma, and further activates downstream AKT/mTOR signaling pathway activity to positively regulate the malignancy of osteosarcoma." (PMID 41145484, 2025). "In vitro rescue assays revealed that FTO overexpression partially reversed TRIM17-induced activation of the AKT/mTOR signaling pathway and attenuated osteosarcoma malignancy." (PMID 41145484, 2025). "As an E3 ubiquitin ligase, TRIM17 promotes FTO ubiquitination and degradation, thereby activating the AKT/mTOR pathway to drive osteosarcoma progression." (PMID 41145484, 2025). "Mechanistically, TRIM17 regulates FTO degradation via ubiquitination, modulates PDK1 gene methylation, and thereby activates the AKT/mTOR signaling pathway, promoting osteosarcoma malignancy." (PMID 41145484, 2025). "The results of cell immunofluorescence showed that TRIM17 and FTO were co-localized in osteosarcoma cells." (PMID 41145484, 2025).
osteosarcoma (continued). "In conclusion, in vivo assays revealed that TRIM17 positively regulates the activation of the AKT/mTOR signaling pathway via FTO-mediated PDK1 expression, thereby enhancing osteosarcoma growth." (PMID 41145484, 2025). "Meanwhile, Western blot results showed that TRIM17 protein levels in osteosarcoma tissues were significantly higher than those in adjacent normal tissues." (PMID 41145484, 2025). "In summary, TRIM17 can interact with FTO, and FTO may regulate the function of TRIM17 in osteosarcoma by influencing the activation of the AKT-mTOR signaling pathway." (PMID 41145484, 2025). "Third, the in vivo assays have limitations: the study relied solely on a nude mouse SC xenograft model and an in vivo metastatic model to validate TRIM17 function in vivo, which does not fully recapitulate the human osteosarcoma microenvironment." (PMID 41145484, 2025). "In conclusion, TRIM17 promotes FTO degradation via ubiquitination, a post-translational modification, and positively modulates the AKT/mTOR signaling pathway, thereby enhancing osteosarcoma malignancy." (PMID 41145484, 2025). "For example, TRIM17 expression was found to be significantly increased in osteosarcoma tissues compared with adjacent nontumorous tissues and TRIM17 is the most frequently amplified of the TRIM genes in breast invasive carcinomas." (PMID 34069831, 2021). "In conclusion, TRIM17 regulates FTO expression by promoting post-translational ubiquitination modification of FTO protein, thereby positively modulating the AKT/mTOR signaling pathway to enhance the clonability and survival potential, migration, and invasion of osteosarcoma." (PMID 41145484, 2025). "Mechanistically, TRIM17 promotes the ubiquitination and degradation of FTO protein, enhances PDK1 mRNA stability via N6-methyladenosine (m6A) modification, and subsequently promotes phosphorylation-dependent activation of the AKT/mTOR signaling pathway, thereby driving osteosarcoma malignancy." (PMID 41145484, 2025). "In conclusion, regardless of whether the basal expression level of TRIM17 in osteosarcoma cells is high or low, overexpression of TRIM17 can significantly promote the clonability and survival potential, migration, and invasion of osteosarcoma in vitro." (PMID 41145484, 2025).